CYP4F2 (cytochrome P450 family 4 subfamily F member 2)
Diseases named in the same sentence as CYP4F2 in open-access papers (continued):
Sharing a sentence is not in itself a finding about the gene and the disease.
lung cancer (4 papers, 2018 to 2023). A malignant neoplasm involving the lung. "Our study aimed to explore the potential association of CYP4F2 gene polymorphisms with lung cancer (LC) risk." (PMID 36998451, 2023). "Stratified analysis found that the rs3093105 and rs3093106 loci of CYP4F2 gene were significantly associated with lower risk of lung cancer (P = 0.012, OR 0.64, 95% CI 0.45–0.91)." (PMID 32350633, 2020). "The frequency of CYP4F2 haplotypes and their association with the risk of lung cancer in subgroups." (PMID 36998451, 2023). "The association of variants in CYP4F2 with lung cancer susceptibility stratified by smoking status." (PMID 36998451, 2023). "The association of variants in CYP4F2 with lung cancer susceptibility stratified by gender." (PMID 36998451, 2023). "We hypothesize that the effect of CYP4F2 gene polymorphisms on the risk for lung cancer may be related to the metabolism of 20-HETE and then affect the growth of cancer cells by regulating the signal pathway of vascular endothelial growth factor." (PMID 32350633, 2020). "Our study has been the first to report that there is a significant correlation between CYP4F2 gene polymorphisms and lung cancer in Chinese Han population, and this is associated with lowered risk of lung cancer in people older than 58 years old, lung adenocarcinoma and men." (PMID 32350633, 2020). "Overexpressed CYP4F2 in non‐small cell lung cancer promotes AA metabolism, which leads to CD8+ T‐cell infiltration and immunosuppression." (PMID 37746665, 2023). "Our research confirms that CYP4F2 and CYP3A5 gene polymorphisms are associated with the risk of lung cancer." (PMID 32350633, 2020). "Four single-nucleotide polymorphisms of the CYP4F2 and CYP3A5 genes were genotyped, and their correlations with the risk of lung cancer were examined using Chi-square test and logistic regression analysis." (PMID 32350633, 2020). "Database prediction found that CYP4F2 was highly expressed in lung cancer tissues." (PMID 36998451, 2023). "CYP4F2 and CYP3A5 gene polymorphisms are associated with the reduced risk of non-small cell lung cancer, and its correlation is related to patients’ age and sex and pathological type of lung cancer." (PMID 32350633, 2020). "However, little research has been done about the association between CYP4F2 and CYP3A5 gene polymorphisms and lung cancer in the Chinese Han population of mainland China." (PMID 32350633, 2020). "This study aimed to explore whether the polymorphisms of CYP4F2 and CYP3A5 are correlated with the risk of lung cancer development." (PMID 32350633, 2020). "Therefore, in this study, four SNP locus in CYP4F2 and CYP3A5 genes were analyzed to explore the association between the polymorphisms of CYP4F2 and CYP3A5 genes and the risk for lung cancer." (PMID 32350633, 2020). "We believe that our results will encourage more people using larger sample sizes to further confirm the relationship between CYP4F2 and CYP3A5 genes and lung cancer, as well as their specific mechanisms in the occurrence and development of lung cancer in the future studies." (PMID 32350633, 2020). "Therefore, CYP4F2 can be used as a new target to improve the therapeutic efficacy of anti‐programmed death receptor‐1 (PD‐1) therapy, and the combination of CYP4F inhibitors and PD‐1 inhibitors will be a new combination drug strategy for lung cancer immunotherapy." (PMID 37746665, 2023).
non-small cell lung carcinoma (3 papers, 2020 to 2025). A group of at least three distinct histological types of lung cancer, including non-small cell squamous cell carcinoma, adenocarcinoma, and large cell carcinoma. "Relative studies demonstrate that 20-HETE (CYP4F2-related products) was associated with the growth of tumors in mouse non-small cell lung cancer cell lines." (PMID 32350633, 2020). "In 2018, rs2074900 in CYP4F2 was found to be significantly related to therapeutic responses to erlotinib in sixty Han Chinese advanced non-small cell lung cancer patients received erlotinib monotherapy." (PMID 32295578, 2020). "CYP4F2 rs2074900 was recently reported to be related to therapeutic responses to erlotinib in sixty Han Chinese advanced non-small cell lung cancer patients received erlotinib monotherapy, illustrating that it may take part in the pathological process of pulmonary disease." (PMID 32295578, 2020).
age-related macular degeneration (2 papers, 2016 to 2021). Age-related loss of vision in the central portion of the retina (macula), secondary to retinal degeneration. "We found no studies analyzing the CYP4F2 (1347C>T, rs2108622) gene polymorphism in patients with age-related macular degeneration; thus we can only compare the genotyping results in our control group with results obtained in other studies." (PMID 27652291, 2016).
atrial fibrillation (2 papers, 2018 to 2020). A disorder characterized by an electrocardiographic finding of a supraventricular arrhythmia characterized by the replacement of consistent P waves by rapid oscillations or fibrillatory waves that vary in size, shape and timing and are accompanied by an irregular ventricular response. "We aimed to assess impact of three important genes participating in vitamin K cycle (i.e. VKORC1 rs9923231, CYP4F2 rs2108622 and NQO1 rs1800566) on the daily stable warfarin dose requirement in Sichuan Han Chinese patients with catheter ablation of atrial fibrillation." (PMID 29776386, 2018).
cerebrovascular diseases (2 papers, 2018 to 2023). "We performed a meta-analysis to assess the potential role of rs1558139 C/T and rs2108622 G/A polymorphisms of CYP4F2 in the risks of cardiovascular and cerebrovascular diseases." (PMID 29426278, 2018). "Considering the conflicting conclusions, we quantitatively measured the genetic correlation between CYP4F2 SNPs and the risk of cardiovascular and cerebrovascular diseases via meta-analysis based on the publicly published data." (PMID 29426278, 2018). "Inconsistent conclusions have been reported for the genetic relationship between CYP4F2 (Cytochrome P450 Family 4 Subfamily F Member 2) polymorphisms and the susceptibility to cardiovascular and cerebrovascular diseases." (PMID 29426278, 2018). "Additionally, there is no meta-analysis regarding the role of CYP4F2 rs2108622 in the risk other cardiovascular and cerebrovascular diseases." (PMID 29426278, 2018).
Cirrhosis (2 papers, 2024). A chronic disorder of the liver in which liver tissue becomes scarred and is partially replaced by regenerative nodules and fibrotic tissue resulting in loss of liver function. "In liver samples of cirrhosis, CYP4A22 increases while CYP4A11 and CYP4F2 decrease." (PMID 39959811, 2024). "In addition, the CYP4F2 and CYP4F3a genes were increased in patients with steatosis, MASH, and cirrhosis." (PMID 40452921, 2024).
endothelial dysfunction (2 papers, 2021 to 2023). In vascular diseases, endothelial dysfunction is a systemic pathological state of the endothelium (the inner lining of blood vessels) and can be broadly defined as an imbalance between vasodilating and vasoconstricting substances produced by (or acting on) the endothelium. "The CYP4F2 protein belongs to the P450 superfamily and is associated with the production of 20-HETE thus influencing endothelial dysfunction, vascular oxidative stress, and high peripheral vascular resistance." (PMID 34577897, 2021).
fatty liver disease (2 papers, 2014 to 2018). A reversible condition wherein large vacuoles of triglyceride fat accumulate in liver cells via the process of steatosis. "This hydrolase plays a role in the conversion ofarachidonic acid to 20-hydroxyeicosatetraenoic acid (20-HETE), and thereby,CYP4F2 reduces the fatty acid metabolite content and also is a preventing factorof lipotoxicity in fatty liver disease by regulation of the fatty acidmetabolism." (PMID 29658965, 2018).
hyperlipidemia (2 papers, 2014 to 2016). "For instance, CYP4F2 is involved in the production of 20-hydroxyeicosatethraenoic acid (20-HETE), a molecule that is proinflammatory and can induce hyperlipidemia." (PMID 24759732, 2014).
Obesity (2 papers, 2016 to 2020). Accumulation of substantial excess body fat. "Other studies showed that genistein (flavonoid) contributes to obesity control by regulating the transcriptional expression of fatty acid ω-hydroxylase (CYP4F2) through the manipulation of CaMKK." (PMID 26811496, 2016).
pancreatic ductal adenocarcinoma (2 papers, 2020 to 2023). An infiltrating adenocarcinoma that arises from the epithelial cells of the pancreas. "A similar study showed that CYP4F2 expression was higher in pancreatic ductal adenocarcinoma (PDA) patients than in normal ones and negatively correlated with age." (PMID 36998451, 2023).
steatosis (2 papers, 2024). Increased lipid within the cytoplasm of cells. "Our data indicate that both CYP4A11, CYP4A22, and CYP4F2 mRNA levels increase in steatosis while both CYP4A11 and CYP4A22 increase in steatohepatitis." (PMID 39959811, 2024).
alcoholic fatty liver disease (1 paper, 2021). Lipid infiltration of the hepatic parenchymal cells that is due to alcohol abuse. "Sterol regulatory element-binding proteins can transactivate CYP4F2 transcription in hepatocytes, and decrease SREBP-1 proteins expression, resulting in reduced expression of CYP4F2, which slows the breakdown of α-Toc in experimental non-alcoholic fatty liver disease model mice." (PMID 33920342, 2021).
breast carcinoma (1 paper, 2025). "As already described for CYP4F2, both CYP4F2 and CYP4F11 are associated with ER+ breast cancer and are regulated by estrogen." (PMID 40858268, 2025). "Recently, a link between CYP4F2 and CYP4F11 expression and the progression of estrogen receptor-positive (ER+) breast cancer was established." (PMID 40858268, 2025). "As observed for CYP4F2, the genetic ablation of CYP4F11 led to a decreased proliferation of a breast cancer cell line with reduced reduction of 20-HETE." (PMID 40858268, 2025).
contact dermatitis (1 paper, 2023). An inflammatory skin condition caused by direct contact between the skin and either an irritating substance or an allergen. "In the transcriptome data of contact dermatitis, the expression of CYP4F2 reduced significantly." (PMID 37741847, 2023).
deep vein thrombosis (1 paper, 2017). "However, deep vein thrombosis decreased association of CYP4F2*3 and CES2 rs4783745." (PMID 28638342, 2017).
depression (1 paper, 2025). "The drug-gene interaction analysis focused on LILRA5, CYP4F2, and KISS1R, which are implicated in the comorbidity of depression and renal failure." (PMID 40595897, 2025). "Further, protein-protein interaction (PPI) network analysis pinpointed five central genes CYP4F2, KCNA3, KISS1R, LILRA5, and ZC3H12D as pivotal players in the shared pathophysiology of depression and renal failure." (PMID 40595897, 2025). "We discovered that the five key genes CYP4F2, KCNA3, KISS1R, LILRA5 and ZC3H12D remained different after Venn diagram overlap of DEGs across depression and renal failure datasets." (PMID 40595897, 2025). "The expression trends of these genes showed general consistency, except for KCNA3 in depression and ZC3H12D and CYP4F2 in renal failure exhibiting opposite expression patterns." (PMID 40595897, 2025). "PPI network analysis identified 23 hub genes, including CYP4F2, KCNA3, KISS1R, LILRA5, and ZC3H12D, as key players in the shared pathophysiology of ESRD and depression." (PMID 40595897, 2025). "PPI network analysis identified CYP4F2, KCNA3, KISS1R, LILRA5, and ZC3H12D as key players in the shared pathophysiology of ESRD and depression." (PMID 40595897, 2025). "Notably, LILRA5, CYP4F2, and KISS1R consistently exhibited higher expression levels in the disease groups compared to controls, suggesting their prominent roles in the pathophysiology of depression and chronic nephritis." (PMID 40595897, 2025).
ichthyosis (1 paper, 2020). Disorders of cornification that are characterized by visible scaling and/or hyperkeratosis of most or all of the skin. "Additionally, 15 genes involved in lipid metabolism were differentially expressed, some directly involved in ichthyosis, e.g., ABCA12, ALOX5, ALOX12B, ALOXE3, CYP4F2, and 2 elongation of very long chain fatty acid protein (ELOV) genes." (PMID 32544098, 2020).
Kawasaki disease (1 paper, 2019). A rare inflammatory disease characterized by an acute febrile, systemic, self-limiting, medium-vessel vasculitis primarily affecting children. "While the influences of CYP2C9, VKORC1, and CYP4F2 for warfarin dosage are not determinate in pediatric patients with Kawasaki disease." (PMID 30121860, 2019). "This study aimed to determine non-genetic and genetic (CYP2C9, VKORC1, CYP4F2) factors affecting warfarin dose in Kawasaki disease." (PMID 30121860, 2019). "This study assessed the associations of warfarin dose with genetic and non-genetic variables in children with Kawasaki disease, with appropriate control groups in order to compare genotype mutations of CYP2C9, VKORC1, and CYP4F2." (PMID 30121860, 2019).
liver failure (1 paper, 2023). A liver disease characterized by the liver losing or has lost all of its function. "However, recent data indicate that the two cytochrome isoenzymes CYP2J2 and CYP4F2 metabolize linezolid which may be influenced by liver failure and thus could explain the reduced body clearance in ACLF as shown in our study." (PMID 37698659, 2023).
optic neuritis (1 paper, 2018). Optic neuritis is inflammation of the optic nerve, the nerve that carries the visual signal from the eye to the brain.The conditionmay cause sudden, reduced vision in the affected eye(s). "The aim of our research was to find the association of IL-17A and CYP4F2 rs1558139 gene polymorphism with optic neuritis." (PMID 29736281, 2018). "We have not found similar studies investigating CYP4F2 gene polymorphisms in patients with optic neuritis." (PMID 29736281, 2018). "Our study showed that CYP4F2 gene rs1558139 polymorphism did not reveal any differences in the distribution of G/G, G/A, and A/A genotypes between groups (35.0% versus 45.0% versus 20.0% in patients with optic neuritis, 30.5% versus 47.0% versus 22.5% in control group, resp)." (PMID 29736281, 2018).
prostate carcinoma (1 paper, 2025). A carcinoma that arises from epithelial cells of the prostate gland. "Research has shown that androgens can significantly increase the expression of CYP4F2 and CYP4F3 through androgen receptor (AR) in prostate cancer cells, while PON1 activity is modulated by estrogen through HDL metabolism pathways." (PMID 40115349, 2025).
pulmonary edema (1 paper, 2023). Accumulation of fluid in the lung tissues causing disturbance of the gas exchange that may lead to respiratory failure. "A comprehensive search in PubMed, Embase, and the China National Knowledge Infrastructure databases was conducted using the search terms: “CYP4F2 and HAPE/ High altitude pulmonary edema”." (PMID 36634101, 2023).
venous thromboembolism (1 paper, 2012). Occlusion of the lumen of a vein by a thrombus that has migrated from a distal site via the blood stream. "The aim of this study is to evaluate the effectiveness and efficiency of an acenocoumarol dosing algorithm developed by our group which includes demographic, clinical and pharmacogenetic variables (VKORC1, CYP2C9, CYP4F2 and ApoE) in patients with venous thromboembolism (VTE)." (PMID 23237631, 2012).
cancer (7 papers, 2015 to 2025). A tumor composed of atypical neoplastic, often pleomorphic cells that invade other tissues. "This study presents the first link between CYP4F2 and immune evasion in cancer, but future work is necessary to reveal the exact CYP4F2 function and how this can be extended to the other CYP4F isoforms." (PMID 40858268, 2025). "CYP4F2-mediated 20-HETE production also triggered the production of interleukin-6 (IL-6) and TGF-β in cancer-associated fibroblasts (CAF) leading to immune evasion through the GPR75-STAT3-c-Jun axis." (PMID 40858268, 2025). "Thus, future studies need to address the cancer-specific action of CYP4F2 for the future development of targeted therapies." (PMID 40858268, 2025). "However, the respective role of CYP4F2 seems to be different in different cancer types." (PMID 40858268, 2025). "Unlike the MethSig cancer genes with an MR/MN smaller than 1, three of the 52 MethSig cancer genes with an MR/MN greater than 1 (CYP4F2, MSC and EIF5A2) were associated with worse survival in a multivariate Cox analysis (P = 0.022 for CYP4F2, P = 0.02 for MSC and P = 0.011 for EIF5A2)." (PMID 40931149, 2025). "CATG00000038715 is near CYP4F2 and CYP4F11, encoding members of the cytochrome P450 enzyme superfamily, and the expression levels of CATG00000038715 and CYP4F2 are most highly correlated in PCa (R = 0.91, p < 2.2e-16) suggesting specificity for this cancer type." (PMID 34311724, 2021).
cardiovascular diseases (5 papers, 2014 to 2023). "Several researches have displayed that genetic polymorphisms in CYP4 family genes such as CYP4A11 and CYP4F2 are related to the susceptibility to cardiovascular diseases." (PMID 36437455, 2022). "Various studies have revealed that single nucleotide polymorphisms (SNPs) in CYP4A11 and CYP4F2 have an impact on expression or catalytic activity of these enzymes, thereby contributing to the molecular basis of cardiovascular disorders including CAD." (PMID 29484037, 2018). "CYP4A11 and CYP4F2 are highly polymorphic genes which became attractive candidates for association studies of cardiovascular diseases." (PMID 29484037, 2018). "Single nucleotide polymorphisms (SNPs) in the VKORC1, CYP4F2, and GGCX genes have been linked to clinical outcomes, such as bleeding and cardiovascular diseases." (PMID 37653796, 2023).
tumor (4 papers, 2022 to 2025). "In poor-prognosis luminal A tumours, for example, overexpression of CYP4F2 can metabolically suppress T-cell function, thereby undermining immune surveillance and facilitating immune evasion even in the presence of a favourable WWOX/HIF1A ratio." (PMID 41007296, 2025). "However, we identified an exception in poor-prognosis luminal A tumours, where CYP4F2 overexpression metabolically suppresses T-cell function—undermining immune surveillance even with favourable ratios." (PMID 41007296, 2025). "The study evaluated both overexpression and knockout of CYP4F2 and CYP4F11 and their effects on cell proliferation, apoptosis and tumour growth." (PMID 40858268, 2025). "General unselective CYP4F inhibition, not of CYP4F2 specifically, improves the efficacy of anti-PD-1 therapy in tumours resistant to immunotherapy." (PMID 40858268, 2025).
CYP4F2 also shares sentences with these, for which no sentence is quoted: cerebral infarction (4 papers); myocardial infarction (4); heart failure (3); Hyperglycemia (2); ovarian carcinoma (2); acute coronary syndrome (1); chronic kidney disease (1); chronic obstructive pulmonary disease (1); Crohn disease (1); diabetic kidney disease (1); essential hypertension (1); heart disease (1); hemorrhagic stroke (1); hypothyroidism (1); lung adenocarcinoma (1); metachromatic leukodystrophy (1); nonalcoholic fatty liver disease (1); Nonalcoholic Steatohepatitis (1); periapical abscess (1); pulmonary disease (1); renal failure (1); respiratory disease (1); thromboembolic disease (1).